S100A9 (S100 calcium binding protein A9)
Diseases named in the same sentence as S100A9 in open-access papers (continued):
Sharing a sentence is not in itself a finding about the gene and the disease.
Sepsis (continued). "These novel findings suggest that S100A9 plays an important pro-inflammatory role in sepsis and could be a useful target to protect against the excessive inflammation and lung damage associated with the disease." (PMID 34884728, 2021). "Because exosomes contents share some of the transcriptomic and proteomic signature of the parent cell, we wondered whether exosomes shed from late sepsis Gr1+CD11b+ MDSCs could be used to identify mediators that promote S100A9 nuclear localization." (PMID 33335790, 2020). "Our previous study showed that genetic deletion of S100A9 in mice improved late sepsis survival." (PMID 33335790, 2020). "In addition, elevated levels of S100A9 and S100A12 proteins in amniotic fluid are associated with elevated inflammatory markers in cord blood and an increased risk for early onset sepsis (EOS)." (PMID 32612607, 2020). "Importantly, Hotairm1 knockdown in late sepsis Gr1+CD11b+ MDSCs prevented S100A9 cytosol to nuclear transfer and decreased repression of proimmune T cells." (PMID 33335790, 2020). "S100A8 and S100A9 have implication on “inflammatory response”, “macrophage activation” and “neutrophil activation” These molecules may serve as signature of sepsis." (PMID 32922168, 2020). "Notably, ectopic expression of Hotairm1 in early sepsis Gr1+CD11b+ cells shuttled S100A9 to the nucleus and promoted the MDSC repressor phenotype." (PMID 33335790, 2020). "Notably, exosomes derived from late sepsis Gr1+CD11b+ MDSCs decreased S100A9 secretion significantly." (PMID 33335790, 2020). "To test whether Hotairm1 can bind S100A9 protein, we performed RNA-immunoprecipitation with cell lysates from late sepsis Gr1+CD11b+ cells." (PMID 33335790, 2020). "This is because a swift increase in the level of IL-6 was observed during the early phase (1–5 days) of sepsis in both the wild-type and S100A9 knock-out mice, and treatment with anti-IL-6 neutralizing antibodies was very efficient at decreasing the expansion of MDSCs in the early septic phase only." (PMID 32931721, 2020). "Thus, we propose that S100A9 and leptin represent tools to reduce calprotectin with putative beneficial outcomes in several maladies, including sepsis and autoimmunity." (PMID 31391467, 2019). "The findings of thisstudy support therapeutic targeting of S100A9 for chronic sepsis." (PMID 29204146, 2017). "We further examined whether S100A9 expression correlateswith sepsis prognosis for the late septic group." (PMID 29204146, 2017). "Thesefindings suggest that S100A9 expression may promote late sepsis immunosuppression andpredicts that its genetic reduction would limit MDSC repressor cells." (PMID 29204146, 2017). "This suggests that the single measurement of either S100A8 or S100A9 mRNA levels may be useful for evaluating their response and for use as a potential biomarker in sepsis." (PMID 24956170, 2014). "Our results suggest that S100A8 and S100A9 mRNA levels may be used as surrogate markers of endotoxin tolerance after sepsis." (PMID 24956170, 2014). "Therefore, the goal of our study was to study the regulation of S100A8 and S100A9 mRNA levels in an ex vivo model of endotoxin tolerance, which is known to partially reproduce sepsis-induced innate immune alterations." (PMID 24956170, 2014). "As S100 proteins have been defined as clinical markers of inflammation in a previous study, S100a8 and S100a9 levels in the lymph may be a marker for the diagnosis of early stage sepsis." (PMID 25242054, 2014). "In this regard, cells from patients with FMF had high levels of S100A8 and S100A9 alarmins but not cells from patients with other inflammatory disorders like sepsis, where these molecules act as ligands for TLR4 and cause strong inflammatory responses within tissues." (PMID 39335710, 2024). "Therefore, the present study aimed to explore the effect of S100A9 on sepsis-induced ALI." (PMID 36768433, 2023).
Sepsis (continued). "Since AMP-activated protein kinase (AMPK) is a critical regulator of glucose and fatty acid (FA) metabolism and exerts a key role in protection against sepsis-induced hepatic injury, we then examined whether S100A9 KO triggers the activation of AMPK and mitochondrial energy metabolism." (PMID 36768433, 2023). "Here, our study further demonstrated that the pharmacological inhibition of S100A9 with Paq effectively improved sepsis-induced liver injury and mitochondrial dysfunction in CLP-treated mice, suggesting that blocking S100A9 may be a new therapeutic approach for sepsis-induced liver injury." (PMID 36768433, 2023). "Although S100A9 is mainly known as a soluble inflammatory mediator/alarmin that enhances the inflammatory responses, our studies suggest that, in the context of late sepsis, Hotairm1 can switch S100A9 protein into a nuclear co-factor that supports the MDSC phenotype." (PMID 39665047, 2023). "Notably, the knockdown of Hotairm1 in late sepsis MDSCs results in the re-relocalization of S100A9 in the cytosol, suggesting that Hotairm1 may facilitate S100A9 nuclear localization in MDSCs during sepsis." (PMID 39665047, 2023). "Moreover, we found that S100A9+ monocytes exhibited profound immunosuppressive function on CD4+ T cell immune response and blockade of S100A9 using Paquinimod could partially reverse sepsis-induced immunosuppression." (PMID 37337301, 2023). "Therefore, S100A9 blockade could be considered as a novel therapeutic strategy for lung injury in sepsis." (PMID 33549095, 2021). "It should be mentioned that S100A9 could also regulate other aspects of leukocyte recruitment and further investigation is required to explore the exact role of S100A9 and other alarmins in sepsis and lung injury." (PMID 34884728, 2021). "Thus, S100A9 can contribute to the proinflammatory or anti-inflammatory states typical of sepsis." (PMID 33335790, 2020). "Our data suggest that leptin-induced S100A9 overexpression exerts beneficial actions; yet, this idea is at odds with the fact that S100A9 forms a complex with S100A8, namely calprotectin, that has been shown to exert several deleterious effects including underlying sepsis-induced lethality." (PMID 31391467, 2019). "Thus, S100A9 protein reprograms immatureGr1+CD11b+ myeloid cells into MDSCs in latesepsis, but has no impact on myeloid cell phenotype or functions under normal conditionsor during the early phase of sepsis." (PMID 29204146, 2017). "Literature validation yielded 30 ultra-high confidence therapeutic candidates, including both established sepsis genes (IL10, TREM1, S100A9, NLRP3) and novel targets warranting investigation." (PMID 41071041, 2025). "In the context of sepsis, inhibiting the long noncoding RNA Hotairm1 with GSK-J4 and targeting S100A9 with a peptone antibody can prevent MDSC differentiation and promote MDSC depletion." (PMID 40153575, 2025). "The results showed that the expression of IRAK3, S100A9, TXN and GSTO1 in the sepsis group was increased, while the expression of NFATC2 in the sepsis group was decreased (P < 0.05)." (PMID 40108736, 2025). "Members of the S100 protein family, S100A8, S100A9 and S100A6 are essential to the pathophysiology of sepsis." (PMID 41303672, 2025). "Theseresults demonstrate that the S100A9 protein directly targetsIL-10 and TGF-β promoters in MDSCs during late sepsis." (PMID 40458301, 2025). "In the validation datasets of GSE28750, GSE57065, GSE13904, GSE26378 and GSE26440, the expression of NLRC4, S100A9 and TXN were also significantly higher in the sepsis group." (PMID 40028203, 2025). "We detected S100A9 protein at both IL-10 and TGF-βpromoters in MDSCs during late sepsis and levels of S100A9 bindingsat these promoters were significantly reduced after the knockdown ofS100A9 in MDSCs from wild-type mice." (PMID 40458301, 2025).
Sepsis (continued). "In sepsis-mediated acute liver injury(ALI), S100A9 promotes inflammation by modulating mitochondrial energy metabolism through the AKT-AMPK signaling pathway." (PMID 40478888, 2025). "Among these, we found certain S100 family proteins (i.e. S100A12 and S100A11) exclusively elevated in sepsis samples, while traditional pro-inflammatory S100A8 and S100A9 were similarly expressed in both healthy and sepsis samples." (PMID 40965975, 2025). "The findings revealed that the combination of S100A9 with APACHE II and IL-6 significantly enhanced the ability to predict sepsis-related mortality." (PMID 40478888, 2025). "Inhibition of S100A9 can reactivate CD8+ T-cell-driven antitumor immunity within lymphomas and mitigate the inhibitory effects of MDSCs in the context of sepsis." (PMID 40153575, 2025). "The results showed that the expression of NLRC4, S100A9 and TXN was significantly higher in sepsis patients." (PMID 40028203, 2025). "When S100A9 was combined with APACHE II and IL-6 to predict 28-day mortality in sepsis, the AUC of the combined model increased from 0.78 (95% CI 0.73–0.83, p < 0.001) to 0.84 (95% CI 0.80–0.89, p < 0.001), demonstrating improved predictive performance." (PMID 40478888, 2025). "CatB, VCAM-1, NGAL, S100-A9, prosaposin, and TSP-1 levels were significantly increased in the sepsis group (p < 0.001) compared with those of the controls." (PMID 39049003, 2024). "Examples of genes related to this pathway that were differentially expressed in our sepsis samples include DEFA1, DEFA3, S100A8, S100A9 and RNASE6." (PMID 37731199, 2023). "S100A9 KO mice were constructed and subjected to CLP to further confirm the involvement of S100A8/A9 in the pathogenesis and development of sepsis." (PMID 37978525, 2023). "Our qPCR results and ROC curve analyses confirmed the accuracy of S100A8, S100A9, and CR1 in diagnosing sepsis as well as in predicting in-hospital mortality among patients with sepsis." (PMID 37298316, 2023). "Key genes upregulated during sepsis, including S100A8, S100A9, and CR1, are responsible for cell cycle regulation and immune responses." (PMID 37298316, 2023). "Sepsis was induced in C57BL/6J mice and S100A9-knockout (KO) mice through the cecal ligation and puncture (CLP)." (PMID 37978525, 2023). "Furthermore, blockade of S100A9 can reduce the infiltration and activation of neutrophil and prevent sepsis-related pulmonary edema and tissue damage, suggesting that S100A9 may be a key target for alleviating sepsis-related injury." (PMID 36439140, 2022). "S100A9; LBP; soluble ST2 (sST2), which serves as a decoy receptor for IL-33; and RAGE (also known as AGER) have been used as prognostic biomarkers in sepsis." (PMID 33232303, 2021). "Targeting S100A9 function decreased formation of CXC chemokines in circulation and lungs and attenuated sepsis-induced lung damage." (PMID 34884728, 2021). "Specifically, the expression levels of these 4 genes were increased > 4.0-fold in patients with sepsis compared with those in healthy subjects: ANXA3 (28.1-fold), S100A8 (4.9-fold), S100A9 (4.4-fold), and MMP9 (69.2-fold)." (PMID 32922168, 2020). "Further qRT-PCR validation indicated that four genes are differentially expressed between patients with sepsis and healthy subjects (MMP9, S100A8, S100A9, and ANXA3)." (PMID 32922168, 2020). "Theseresults strongly support that S100A9 sustains both NFI-A and miR-21 and miR-181blevels during late sepsis immunosuppression." (PMID 29204146, 2017). "Another notable pathway expressed at higher levels in sepsis survivors related to the receptor for advanced glycation endproducts (RAGE) pathway and included the RAGE-related genes S100A8, S100A9, S100A12, and formyl peptide receptor 1 (FPR1)." (PMID 25538794, 2014). "In conclusion, the results described here reinforce the central role of MMP-8 in the regulation of neutrophil recruitment to the lungs during sepsis, adding the myeloid-related proteins S100A8 and S100A9 as one of the involved mediators." (PMID 22768176, 2012).
Sepsis (continued). "qPCR results showed that the expression of S100A9, PCBP1, PIK3CB, FOXO1, and TMEM59 was consistent with the public dataset, among which S100A9, PIK3CB, and TMEM59 were significantly overexpressed in sepsis, whereas PCBP1 and FOXO1 were significantly underexpressed in sepsis." (PMID 41542228, 2026). "The results show that S100A8 and S100A9 are important for the progression of sepsis, especially during the non-survivor phase, when they being strongly associated with inflammation and immune system dysregulation." (PMID 41303672, 2025). "Non-surviving sepsis patients exhibited elevated serum S100A9 concentrations than surviving patients." (PMID 40478888, 2025). "The expression of NLRC4, S100A9 and TXN was significantly higher in the sepsis patients." (PMID 40028203, 2025). "Since IL-10 and TGF-β play majorroles in sepsis-induced immunosuppression and because S100A9-defficient mice do notgenerate immunosuppressive MDSCs, weasked whether S100A9 protein induces IL-10 and TGF-βexpression in MDSCs during late sepsis." (PMID 40458301, 2025). "Due to the significant clinical heterogeneity of sepsis patients (including disease progression, treatment differences, etc.), the correlation between dynamic serum S100A9 levels and length of hospitalization was not systematically analyzed in this study." (PMID 40478888, 2025). "In order to verify the validity of the diagnostic marker genes, a KS test was performed on the GSE69063 dataset for these five genes, and the results showed that IRAK3, S100A9, TXN and GSTO1 were up-regulated in the sepsis group, while NFATC2 was down-regulated." (PMID 40108736, 2025). "Synchronously, the serum S100A9 levels of non-surviving and surviving sepsis patients were analysed, and a statistically significant difference was identified across both groups." (PMID 40478888, 2025). "In addition, we identified key genes that were upregulated in sepsis, namely, S100A8, S100A9, and CR1, as well as those that were downregulated, namely, CD79A, HLA-DQB2, PLD4, and CCR7." (PMID 37298316, 2023). "Our data showed that both S100A8 and S100A9 expression were highly upregulated in the liver tissues of CLP-treated mice, suggesting that elevated S100A8/A9 may be involved in sepsis-induced acute liver injury." (PMID 36768433, 2023). "For example, blocking S100A9 with the inhibitor ABR-238901 greatly attenuates the CLP-induced infiltration of neutrophils, formation of edema, and expression of Mac-1, CXCL1, CXCL2 and IL-6 in the plasma or lung and improves sepsis-induced lung injury." (PMID 36768433, 2023). "In this research, using Paquinimod (Paq, also known as ABR25757), an S100A8/A9 specific inhibitor which prevents S100A8/A9 to bind to TLR4, we explored the role of S100A9 in the development of septic AKI in a murine model of cecal ligation and puncture (CLP)-induced sepsis." (PMID 37547329, 2023). "Notably, pDC B, characterized by high expression of S100A8, S100A9, FCN1 and CD14, was the dominant subtype in the ICU-Sepsis group." (PMID 37781404, 2023). "This suggested that the inhibition of S100A9 may improve mitochondrial fission-fusion balance and dysfunction, leading to the inhibition of AKI after sepsis." (PMID 37547329, 2023). "In agreement with our findings, one Chinese prospective cohort study also performed a comprehensive transcriptome profile analysis and qPCR validation, and suggested S100A8, S100A9, and ANXA3 as key genes differentially expressed between sepsis patients and healthy controls." (PMID 37298316, 2023). "Notably, the key genes upregulated during sepsis are responsible for regulating cell cycle progression and differentiation (i.e., S100A8 and S100A9) and immune responses (i.e., ANXA1, APOBEC3A, LILRA5, CR1, and CD55)." (PMID 37298316, 2023). "Because Hotairm1 couples with S100A9 to program MDSCs during later sepsis, our findings underscore the importance of removing H3K4me3 in limiting excessive MDSC accumulation during later sepsis in humans." (PMID 35185915, 2022).
Sepsis (continued). "GSK-J4 treatment resulted in S100A9 relocalization to the cytosol in later MDSCs, similar to early sepsis MDSCs, which are not immunosuppressive." (PMID 35185915, 2022). "Excessive expression of S100A9 has been observed in several infection- and non-infection-induced inflammatory diseases, such as sepsis, myocardial infraction and chronic obstructive pulmonary disease." (PMID 33549095, 2021). "Plasma levels of S100A8 and S100A9 were elevated, as was up-regulation of S100A12, S100A9, and arginase-1 gene expression, in adults with sepsis, compared to non-septic patients in intensive care." (PMID 30555806, 2018). "Whether alarmins, such as S100A8/S100A9, play a role in MDSC expansion and immunosuppression in neonatal sepsis requires further investigation." (PMID 30555806, 2018). "Because S100A9 knockout prevented late sepsis deaths, we first tested whether S100A9deficiency affects MDSC generation during sepsis response." (PMID 29204146, 2017). "Of note,administration of recombinant S100A8 and/or S100A9 at the onset of the late sepsis phasedid not impact sepsis outcomes in the S100A9 knockout mice." (PMID 29204146, 2017). "We further find that S100A8/A9proteins are released from phagocytes during early, but not late sepsis, and thatcytosolic S100A9 translocates from cytosol to the nucleus of MDSCs." (PMID 29204146, 2017). "In contrast, wild-type and S100A9 knockout miceproduced small amounts of the immunosuppressive IL-10 during early sepsis, butsignificantly increased during late sepsis in the wild-type mice and not in knockoutmice." (PMID 29204146, 2017). "Difference in serum S100A9 levels between elderly and non-elderly patients with sepsis." (PMID 40478888, 2025). "Moreover, the expression of S100A9, NLRC4 and TXN were significantly higher in sepsis group." (PMID 40028203, 2025). "Mice lacking the s100a9 gene do not generate MDSCs or develop late/protracted sepsis." (PMID 39665047, 2023). "Interestingly, S100A8/S100A9 have been described to specifically interact with the TLR4-CD14-MD2 complex, thus representing inflammatory components that amplify phagocyte activation during the sepsis upstream of TNF-α-dependent effects." (PMID 35741108, 2022). "However, the role of S100A9 in regulating neutrophil activation, inflammation and lung damage in sepsis is not known." (PMID 34884728, 2021). "The levels of S100A8 and S100A9 were significantly elevated in the sepsis group without treatment." (PMID 32076015, 2020). "Furthermore, silencing the S100A9 in MDSCs during late sepsis abolished their immunosuppressive capability, indicating that the intracellular but not the extracellular S100A9 was responsible for activating immunosuppressive MDSCs." (PMID 32931721, 2020). "Finally, GWAS data were relatively limited and MR Analysis could not be performed to assess whether there is a nonlinear relationship between sepsis and S100A9, TXN and GSTO1 levels." (PMID 40108736, 2025). "However, the role of S100A9 in lung injury in sepsis has not been fully investigated." (PMID 33549095, 2021).